LINC00665 (long independently transcribed non-coding RNA 665)
Diseases named in the same sentence as LINC00665 in open-access papers (continued):
Sharing a sentence is not in itself a finding about the gene and the disease.
tumor (34 papers, 2019 to 2025). "Clinically, SND1-IT1 and LINC00665 are positively associated with greater tumor invasion depth, lymph node metastasis, and higher TNM stage, whereas elevated levels of FBXO18-AS, LINC00665, and NR027113 are indicative of poor prognosis." (PMID 41437175, 2025). "High LINC00665 expression was associated with the advanced tumor size, Edmondson grade, and the poor survival of HCC patients." (PMID 35664776, 2022). "LINC00665 expression was significantly associated with the tumor size and the tumor, node, and metastasis (TNM) stage, but not with the age of the patients." (PMID 32983239, 2020). "The expression of linc00665 in LUAD tumor tissues was closely associated with patients’ aggressive clinicopathological characteristics and could serve as an independent predictor of recurrence-free survival." (PMID 30692511, 2019). "LINC00665 knockdown significantly inhibited tumor growth, and NK cell injection further enhanced this effect (all P < 0.05)." (PMID 38951802, 2024). "We know from previous work that LINC00665 is an oncogenic long non-coding RNA affecting multiple cancer-related signaling pathways via the targeting of tumor suppressive RNAs, such as miR-214-3p and miR424-5p." (PMID 39595048, 2024). "Injections of LINC00665-overexpressing PC9 cells effectively promoted the tumor growth in irradiated mice." (PMID 37830596, 2023). "High expression of LINC00665 is closely related to the clinicopathological features of 10 cancers, including tumor size, depth of invasion, lymph node metastasis, and TNM staging." (PMID 35563845, 2022). "LINC00665 is a tumor-promoting factor, newly discovered in recent years, which has great potential as a diagnostic and prognostic marker for various tumors and is expected to become a therapeutic target for various tumors." (PMID 35563845, 2022). "It has been reported that LINC00665 enhances tumor propagation, proliferation and metastasis via sponging miRNA-1224-5p and subsequent upregulation of SND1." (PMID 35773731, 2022). "LINC00665 functions in many biological processes of tumor cells, such as cell proliferation, migration, invasion, angiogenesis, and metabolism, and is related to the clinicopathological characteristics of cancer patients." (PMID 35356290, 2022). "Further clinicopathological correlation analysis indicated that higher LINC00665 expression was correlated with larger tumor size, later clinical stages, and poorer OS." (PMID 35664776, 2022). "LINC00665 is abnormally expressed in multiple human cancers, and its dysregulation is significantly related to important clinical characteristics, such as tumor size, histological grade, TNM stage, and overall survival rate." (PMID 35356290, 2022). "Secondly, LINC00665 plays a crucial role in various biological processes, including tumor cell proliferation, migration, invasion, apoptosis, autophagy, angiogenesis, and metabolism." (PMID 35356290, 2022). "LINC00665 is remarkably elevated in 106 BCa tissues and cell lines (MDA-MB-231 and MCF-7), and its expression is significantly associated with tumor size and TNM stage." (PMID 35664776, 2022). "In this present investigation, our results suggested that LINC00665 was up-regulated in LUAD tumor tissues compared with adjacent normal lung tissue." (PMID 34277412, 2021). "A series of researches have revealed that Linc00665 is upregulated in a variety of cancers, and can promote tumor progression." (PMID 33738251, 2021). "The influence of LINC00665 overexpression on gemcitabine resistance was also evaluated by tumor formation assay in vivo." (PMID 33436545, 2021). "After evaluating the correlation between the LINC00665 expression and clinicopathological characteristics, we noticed that patients with larger tumor size and later clinical stages presented higher LINC00665 level." (PMID 34306997, 2021). "The results of subcutaneous tumor model in nude mice showed that lung metastases were significantly reduced in Linc00665 knockdown group." (PMID 33738251, 2021).
tumor (continued). "Further, LINC00665 expression was remarkably high in all tumor samples, as determined by qRT-PCR analysis." (PMID 32983239, 2020). "The expression of linc00665 in tumor tissues was significantly higher than that in adjacent normal tissues." (PMID 30692511, 2019). "In conclusion, these data suggest that high linc00665 expression in tumor tissues represents a promising indicator of tumor progression and poor prognosis for LUAD." (PMID 30692511, 2019). "Taken together, these data implied that knockdown of linc00665 inhibited tumor growth and metastasis in vivo." (PMID 30692511, 2019). "qRT-PCR results demonstrated a significant increase in LINC00665 expression in tumor tissues compared to adjacent tissues (both P < 0.05), and metastatic lung cancer patients exhibited significantly higher levels of LINC00665 compared to non-metastatic lung cancer patients (both P < 0.05)." (PMID 38951802, 2024). "In addition to LINC00665, numerous other oncogenes and tumor-suppressive genes have been shown to been dysregulated by aberrant NF-κB signaling." (PMID 35993712, 2022). "Thus, therapies targeted against LINC00665 are expected to decrease tumor volume, reduce malignant features, and improve the response of cancer cells to both chemotherapeutic drugs and targeted therapies." (PMID 36429005, 2022). "In recent years, the role of LINC00665 in tumor has been found gradually." (PMID 35152838, 2022). "Then, it could be concluded that with the further development of the tumor, the expression of LINC00665 gradually increased, which was closely related to clinical diagnosis." (PMID 35350239, 2022). "Furthermore, relatively high expression levels of AC099850.3 and LINC00665 were observed in tumor samples." (PMID 35154469, 2022). "Aberrant expression of LINC00665 is prevalent in human tumor diseases." (PMID 35563845, 2022). "In addition, the level of LINC00665 was related to tumor size, FIGO stage, and lymph node metastasis." (PMID 35356290, 2022). "Additionally, the knock-down of LINC00665 triggered a reduction of LINC00665 expression while an increase of KLF2 protein level in excised tumor masses." (PMID 34094920, 2021). "Previous transcriptome-sequencing studies also indicated that LINC00665 was overexpressed in tumor tissues of CCA patients, thus we further checked the expression of LINC00665 in 100 pairs of CCA samples and matched adjacent-normal tissues collected from Henan Provincial People’s Hospital." (PMID 33436545, 2021). "For instance, more than 20% competitive partner genes of SNHG3 were also regulated by LINC00665, indicating that they may exhibit a similar mechanism in the tumor." (PMID 32849794, 2020). "Further analyses revealed that high linc00665 expression in LUAD tissues was remarkably corrected with larger tumor size (p = 0.0132), advanced TNM stage (p = 0.0363), and lymph node metastasis (p = 0.0066), but not correlated with other features such as age, gender, and differentiation." (PMID 30692511, 2019). "In the present studies, it has been shown that LINC00665 performed the different biological functions in different types of tumors, and some scholars have reported it could act as an oncogene to promote the proliferation and migration of tumor." (PMID 34094920, 2021). "In addition, deletion of LINC00665 expression repressed tumor formation in vivo." (PMID 34804162, 2021). "There was an evident increase in the levels of LINC00665, UCHL3, AhR and PD-L1, but miRNA-582-5p was downregulated in the tumor tissues derived from LINC00665-overexpressing cancer cells." (PMID 37830596, 2023). "LINC00665 displayed high expression in CRC tissues and cells, and promoted tumor progression in vivo." (PMID 35101035, 2022). "In general, these findings imply that LINC00665 functions as a miR-195-5p sponge, regulating MYCBP expression and promoting tumor growth in LUAD." (PMID 34277412, 2021).
tumor (continued). "Further, we determined that LINC00665 is capable of enhancing LUAD cell proliferation, invasion, and migration based on in vitro and in vivo experiments, indicating a tumor promoter role in LUAD." (PMID 34277412, 2021). "On top of that, the pearson correlation analysis revealed a significant relationship between LINC00665 and DOCK1 in AML tumor samples." (PMID 33658535, 2021). "LINC00665 was validated to facilitate CRC cell growth and tumor progression via modulating miR-138-5p/SIN3A, which may offer strong evidence that LINC00665 might act as a potential therapeutic target in CRC treatment." (PMID 35101035, 2022). "Upregulated LINC00665 expression correlated with tumor size and tumor, node, and metastasis stages, but not with the age of patients." (PMID 32983239, 2020). "Knockdown linc00665 dramatically decreased tumor growth in vivo, which was determined by significantly reduced tumor size and weight compared with negative controls." (PMID 30692511, 2019). "First, we utilized qRT-PCR for determining LINC00665 expression in tumor and non-tumor samples." (PMID 35101035, 2022). "Compared with normal tissues, LINC00665 had higher expression in the pathological stages III and IV, tumor-free groups, people no more than 60 years old, and stages T3, T4, N0, N1, and M1." (PMID 35350239, 2022).
cancer (28 papers, 2019 to 2024). A tumor composed of atypical neoplastic, often pleomorphic cells that invade other tissues. "LINC00665 was reported to be significantly dysregulated in cancers and has an important clinical association." (PMID 35664776, 2022). "High expression of LINC00665 was closely associated with clinicopathological features of 10 cancers." (PMID 35563845, 2022). "In this review, we comprehensively summarize the expression level, function, and molecular mechanisms of LINC00665 in different human cancers and emphasize that LINC00665 is a promising new diagnostic, prognostic biomarker, and therapeutic target." (PMID 35356290, 2022). "More importantly, LINC00665 can function as an oncogene by sponging different miRNAs, resulting in cancer-associated gene dysregulation in many cancers." (PMID 34277412, 2021). "In addition, aberrant expression of LINC00665 is closely associated with clinicopathological features and poor prognosis of various cancers." (PMID 35563845, 2022). "Recent studies have found that LINC00665 expression was significantly upregulated in most cancers and could be used as a valuable diagnostic, prognostic, and therapeutic target." (PMID 35664776, 2022). "Aberrant expression of LINC00665 is associated with prognosis in cancer patients." (PMID 35563845, 2022). "Besides, increased LINC0063 and LINC00665 expression were associated with drug sensitivity of cancer cells to AT-133387 and cobimetinib (isomer 1)." (PMID 36281290, 2022). "The observed downregulation of LINC00665 led to a substantial inhibition of cancer cell proliferation, migration, and invasion, coupled with an enhancement of apoptotic processes." (PMID 38951802, 2024). "LINC00665 plays an oncogenic role in multiple processes, including cancer cell proliferation, migration, and invasion through various molecular mechanisms." (PMID 39595048, 2024). "LINC00665 can participate in the regulation of five signaling pathways to regulate cancer progression, including the Wnt/β-catenin signaling pathway, TGF-β signaling pathway, NF-κB signaling pathway, PI3K/AKT signaling pathway, and MAPK signaling pathway." (PMID 39595048, 2024). "In short, the previous research makes us believe that LINC00665 has the potential to become a prognostic marker of human cancers." (PMID 35356290, 2022). "In this review, we summarize the current findings on LINC00665, including its biological roles and molecular mechanisms in various cancers." (PMID 35664776, 2022). "Since its first report in 2018, LINC00665 is found to be aberrantly expressed in more than 10 cancers." (PMID 35563845, 2022). "In conclusion, LINC00665 can regulate the expression of its downstream target genes through competitive binding with miRNAs, thereby acting as an oncogene in various cancers." (PMID 35563845, 2022). "Aberrantly high expression of LINC00665 was discovered in tissues of these three cancers, and consistently, we discovered that LINC00665 was also overexpressed in CRC tissues." (PMID 35101035, 2022). "As an emerging oncogenic factor, abnormal expression of LINC00665 exists in 18 types of cancers, including tumors in multiple human reproductive, digestive, respiratory, neurological, and endocrine systems." (PMID 35563845, 2022). "Current evidence suggests that LINC00665 is a very promising biomarker and target for cancer research." (PMID 35563845, 2022). "This review summarizes the literature on the expression level, roles, and related molecular mechanisms of Linc00665 in cancers, thus pointing out the clinical potential of Linc00665 as a diagnostic, prognostic biomarker, and therapeutic target." (PMID 35356290, 2022). "LINC00665 (also called CIP2A-BP) is a novel lncRNA located on chromosome 19q13.12 and abnormally expressed in many cancers." (PMID 35356290, 2022). "Existing studies also show that the abnormal expression of LINC00665 is closely related to the prognosis of many human cancers." (PMID 35356290, 2022).
cancer (continued). "LINC00665 plays an oncogenic role in cancer cell proliferation, migration, and invasion through various molecular mechanisms." (PMID 35664776, 2022). "LINC00665-mediated regulation of cancer progression involves various mechanisms, including acting as a ceRNA, directly binding to and interacting with proteins, and being an upstream molecule that regulates multiple signaling pathways." (PMID 35356290, 2022). "In the future, it is necessary to further explore the regulatory mechanism of LINC00665 in different cancers and to establish a more refined LINC00665 regulatory network." (PMID 35563845, 2022). "The discovery of CIP2A-BP provides a new direction for future research of LINC00665, which is expected to become a new target in cancer." (PMID 35563845, 2022). "Meanwhile, LINC00665 is involved in the regulatory process of six cancers by directly targeting ten protein-coding genes." (PMID 35563845, 2022). "LINC00665 can regulate five signaling pathways, thereby promoting the occurrence and development of cancer." (PMID 35563845, 2022). "LINC00665 can participate in five signaling pathways to regulate cancer progression, including the Wnt/β-catenin signaling pathway, TGF-β signaling pathway, NF-κB signaling pathway, PI3K/AKT signaling pathway, and MAPK signaling pathway." (PMID 35563845, 2022). "The expression levels of LINC00665 in human cancers and normal tissues were explored using the Genotype-Tissue Expression (GTEx) Project and Gene Expression Profiling Interactive Analysis (GEPIA)." (PMID 35664776, 2022). "Though the majority of studies and our results indicate the upregulation and oncogenic function of LINC00665 in cancers, some other studies provide contrary consequences." (PMID 33436545, 2021). "Up to now, the oncogenic role of LINC00665 in several kinds of cancer has been disclosed through different mechanisms." (PMID 34804162, 2021). "Consistent with the conclusions of previous studies in other cancers, our present study uncovered that LINC00665 is also an oncogene in OS." (PMID 34306997, 2021). "Although many studies have reported the oncogenic function of LINC00665 in multiple cancers, few studies have explored its role in CRC." (PMID 33878735, 2021). "In this study, our results showed that LINC00665 expression level in PCa cancer tissues was significantly up-regulated, compared with that in adjacent ones." (PMID 34094920, 2021). "LINC00665 is frequently dysregulated in multiple cancers, and there are more and more studies focused on the potential function of LINC00665 in cancer progression and chemoresistance in recent years." (PMID 33436545, 2021). "LINC00665 is located at chromosome 19q13.12 and many studies have demonstrated that LINC00665 serves as an oncogene in cancer progression." (PMID 33407473, 2021). "These contrary results reveal the complexity and heterogeneity between cancers of different origin and the diverse functions of LINC00665 in different cancers." (PMID 33436545, 2021). "Consistently, the data analysis from Cancer RNA-seq Nexus inducing TCGA database showed that linc00665 was significantly upregulated in all stages of LUAD tissues." (PMID 30692511, 2019). "Recent studies have found that LINC00665 expression was significantly up-regulated in many cancers." (PMID 39595048, 2024). "Both TAF15 and LINC00665 were downregulated in glioma carcinoma tissues and cancer cells." (PMID 35563845, 2022). "In addition, LINC00665 can directly target 10 protein-coding genes to regulate the occurrence and development of various cancers." (PMID 35563845, 2022). "lncRNA LINC00665 has been proven to play a vital role in many cancers." (PMID 35251139, 2022). "Finally, abnormal expression of LINC00665 can not only affect the occurrence and development of cancers but also affect or predict the sensitivity of human cancers to chemoradiotherapy." (PMID 35356290, 2022).